CXCL10 (C-X-C motif chemokine ligand 10)
Diseases named in the same sentence as CXCL10 in open-access papers (continued):
Sharing a sentence is not in itself a finding about the gene and the disease.
melanoma (continued). "CXCL10, known as interferon γ-induced protein 10 (IP-10), has been reported in multitudinous tumors and autoimmune diseases, including breast carcinoma, melanoma, sarcoma, and colon cancer." (PMID 37484915, 2023). "Overall, these data highlight a defective intracellular IFN-α and CXCL10 production in pDCs exposed to melanoma soluble factors." (PMID 38239354, 2023). "One of them demonstrated that CXCL10 can be produced not only by immune cells but also by melanoma cells after the application of immunotherapy, which is a prognostic benefit for the tumor." (PMID 37187618, 2023). "Similar to our observations in human melanoma cell lines, CXCL10 was upregulated in mouse melanoma tumors following demethylation-mediated reactivation of STING signaling." (PMID 36949064, 2023). "BRAF mutated patients had significantly higher expression of APRIL/TNFSF13 and CXCL10 in comparison to BRAF wild-type patients, while NRAS wild-type patients had higher expression of TNFSF13 in comparison to patients with melanomas harboring NRAS mutations." (PMID 37435077, 2023). "Mechanistically, ZEB1high melanoma cells showed a defective secretion of T cell-attracting chemokines, including CXCL10, suggesting the intrinsic role of ZEB1 in regulating the secretome and subsequent immune cell attraction." (PMID 35432344, 2022). "There are also studies associating the CXCL10/CXCR3 gene expression pathway with enhanced metastatic potential and poor prognosis in patients with melanoma and colon cancer." (PMID 35296026, 2022). "Knocking-out the epigenetic regulators Arid2 or Pbrm1 in B16F10 melanoma cells significantly increased CXCL9/CXCL10 production and CD8+ infiltration in vivo, resulting in decreased tumor growth." (PMID 35432344, 2022). "In vitro, melanoma cell lines M537 produced CXCL9 and CXCL10 which was associated CD8+ effector T cells." (PMID 35626062, 2022). "The CXCR3 ligands CXCL9 and CXCL10 also have been successfully delivered via viral-vectors in colon and melanoma mouse models." (PMID 35626062, 2022). "The same observation was made in a melanoma BM model where astrocytes secrete CXCL10, promoting migration of melanoma BM cells expressing CXCR3, the CXCL10 receptor." (PMID 35884845, 2022). "Taken together, melanoma cells secreted a variety of proinflammatory factors, mainly cytokines, such as IL-1β and IL-8, and chemokines, such as CXCL10, CXCL11, and CCL20, during CIS, while during TIS, melanoma cells produced lower levels of SASP proteins." (PMID 35563820, 2022). "In melanoma patients, baseline levels of CXCL9, CXCL10, and CXCL11 were associated with response to anti-PD-1 therapy." (PMID 35626062, 2022). "The predictive model created in this work comprises five inflammatory response-related genes: C3AR1, CXCL10, EIF2AK2, EMP3, and ICAM1, all of which are all overexpressed in melanoma tissue and are associated with a poor prognosis." (PMID 35982458, 2022). "In a recently published work with in situ staining of RNA transcripts and proteins in baseline biopsies of melanoma patients, we found that the major cellular source of CXCL10 was indeed CD45+ immune cells in humans." (PMID 35626062, 2022). "Chemokines CXCL9 and CXCL10 are well described mediators for activated T cell homing in melanoma through their interaction with receptor CXCR333,34." (PMID 35013216, 2022). "We also found that primary melanoma or metastatic melanoma patients with higher levels of CXCL10 expression exhibited more CD8+ T cell infiltration." (PMID 35145233, 2022). "Simultaneous reduction of CXCR3, CXCL9, and/or CXCL10 expression suppresses cancer metastasis rates in melanoma, CRC,310 and breast cancer models." (PMID 35702353, 2022). "We have further built on these findings by demonstrating the role of GPR182 scavenging of CXCL9 and CXCL10 by LECs in the TME of murine melanoma, implicating lymphatic GPR182 as a potential therapeutic target in cancer immunotherapy." (PMID 35013216, 2022).
melanoma (continued). "Studies using a melanoma brain metastasis immunocompetent mouse model revealed an upregulation in proinflammatory cytokines CXCL10, CCL17, CCL2, IL6, and IL-1β." (PMID 33466236, 2021). "The baseline concentration of IFNγ-inducible chemokine CXCL10 was higher in melanoma, whereas higher serum concentrations of MICA and MICB-both soluble NKG2D ligands-were detected in UC." (PMID 34071888, 2021). "Mast cells are an essential source of CXCL10, and CXCL10 plays a vital role in melanoma’s immune defense." (PMID 33540700, 2021). "In this study, the immune-regulatory ability of melanoma CAFs was demonstrated by the ample production of several cytokines and chemokines, including IL-1α, IL-1β, IL-6, IL-8, and CXCL10." (PMID 34298873, 2021). "Melanoma patients treated with immunotherapy had significantly better survival rates when the tumor expressed CXCL9 or CXCL10." (PMID 34206510, 2021). "In line with this, higher serum concentrations of CXCL10, an IFNγ-inducible chemokine involved in T-cell recruitment to the tumor, were measured in melanoma compared to UC." (PMID 34071888, 2021). "Levels of pro-inflammatory cytokines and chemokines including CXCL10, IFNα, IFNβ, IL-1b and TNFα increased with treatment in the majority of the melanoma tumoursphere lines tested." (PMID 34359633, 2021). "A previous report suggested a potential role of DPP-4 inhibition in CXCL10-mediated lymphocyte trafficking in melanoma B16F10-bearing mice." (PMID 34631556, 2021). "Levels of CXCL9 and CXCL10 were also correlated with the presence of tumor-infiltrating T cells in melanoma patients and migration assays confirmed that these chemokines were critical for T-cell influx." (PMID 34203869, 2021). "In melanoma, modest increases in the serum concentration of CXCL10 and Kyn/Trp were observed, while the frequency of B-cells decreased, but these changes were not significantly different to the observed trend before SBRT." (PMID 34071888, 2021). "High levels of CXCL9 and CXCL10 expression in lymph nodes can promote melanoma cell metastasis through the CXCR3 signaling." (PMID 33407095, 2021). "CXCR3 is not only essential for T-cell trafficking to melanoma but can improve NK-cell infiltration of CXCL10-producing tumours." (PMID 34830780, 2021). "When CXCL10 is administered via an adenovirus vector in mouse models of melanoma, reduced tumour growth is seen." (PMID 34830780, 2021). "Similar findings have been reported for cisplatin and DTX, which promoted lymphocyte recruitment and infiltration within tumor by inducing melanoma cells to express CXCL10 and CXCL11, respectively." (PMID 34712615, 2021). "In a xenograft-harboring mouse model of CXCL10-transfected melanoma, overexpression of CXCR3 on NK cells after ex vivo growth with irradiated EBV-LCL feeder cells and IL-2 resulted in better trafficking and antitumor activity." (PMID 34970253, 2021). "Barreira da Silva and colleagues have shown that DPP-4 inhibition preserved the active form of chemokine CXCL10, which enhanced T-cell accumulation and immunity, resulting in diminished growth of murine melanoma and colon cancer." (PMID 36860286, 2021). "In vivo tumor-transplant models showed that the DPP4 inhibitor sitagliptin reduced tumor growth through the preservation of bioactive CXCL10 in the TME of melanoma and colon carcinoma." (PMID 33757558, 2021). "In a similar study using an in vivo xenograft model, it was demonstrated that activated CXCR3-positive human NK cells selectively migrate towards CXCL10-positive human melanoma tumor cells." (PMID 34768814, 2021). "The chemokines that signal through CXCR3, including CXCL9 and CXCL10, have been suggested to promote T-cell infiltration and activation in melanoma and other solid tumors." (PMID 34203869, 2021). "An increased CXCL10 and its corresponding receptor, CXCR3, are positively associated with malignant melanoma, ovarian carcinoma, multiple myeloma, B-cell lymphoma, and basal cell carcinoma." (PMID 34683090, 2021).
melanoma (continued). "Particularly, CXCL9 and CXCL10 expression in the lymph nodes is reported to promote CXCR3-mediated metastasis of melanoma cells." (PMID 33195424, 2020). "In the KEYNOTE-001 study, six gene signatures of INFG-related genes (IDO1, HLA-DRA, STAT1, CXCL9, IFNG and CXCL10) were previously developed in melanoma patients." (PMID 32107458, 2020). "For example, Sitagliptin treatment improves anti-tumour responses via enhanced CCL11-mediated eosinophil migration in hepatocellular carcinoma mouse models, and promotes CXCL9- and CXCL10-mediated dendritic cell trafficking to melanoma tumours." (PMID 33143089, 2020). "On the other hand, neither the high LDH serum level nor the elevated tumor burden directly affected the pDC capability to produce IFN-α and CXCL10, recognizing their poor values as reliable biomarkers for pDC dysfunction in melanoma patients." (PMID 32731406, 2020). "Two other studies reported that deletion of some other key autophagy genes, FIP200 or BECN1, led to increased CXCL10 production in mammary tumor cells or melanoma cells." (PMID 32582551, 2020). "It has also been observed that CXCL10 directly limits cancer (melanoma) growth in vivo and in vitro." (PMID 32547545, 2020). "An additional study reports a significant expression change of six chemokines (namely, CCL2, CCL3, CCL4, CCL5, CXCL9, and CXCL10) related to the lymphocyte infiltration in the melanoma tissue." (PMID 33302400, 2020). "In melanoma, the presence of CXCR3 ligands such as CXCL9, CXCL10, and CXCL11 has been associated with enhanced CD8+ T cell infiltration and hence, better survival prognosis." (PMID 32486450, 2020). "Following adoptive transfer of these ex vivo expanded human NK cells, mice bearing CXCL10+ melanoma tumors had increased intratumoral infiltration of NK cells and a significantly prolonged survival compared with mice bearing CXCL10− tumors." (PMID 30805309, 2019). "High pre-treatment expression of IFN-γ or IFN-γ-inducible factors, such as CXCL9, CXCL10, or CXCL-11, was associated with response in melanoma patients." (PMID 31731645, 2019). "Functional STING signaling activation was examined in STING-positive melanoma cell lines upon stimulation with the agonist 2’3’-cGAMP by measuring the induction of CXCL-10 and IFN-beta." (PMID 30400822, 2018). "In contrast, CXCR3+ NK cells infiltrated tumor tissue in murine lymphoma and melanoma models in a CXCL10-dependent manner." (PMID 30319622, 2018). "Gene transfer of CXCL10 by pCLNCX retroviral vectors in melanoma xenograft models decreased angiogenesis and tumor growth." (PMID 30319622, 2018). "In the present report, the group that was infected with T. spiralis and challenged with a melanoma cell line showed a greater reduction of CXCL10 production in comparison with the other group that was only infected with T. spiralis." (PMID 30266743, 2018). "Our findings reveal an increase of secreted CXCL10 and ATP into the extracellular environment following combination treatment in melanoma cells." (PMID 30518936, 2018). "For example, in melanoma, the upregulation of chemokine genes, such as Ccl2, Ccl3, Ccl4, Ccl5, Cxcl9, and Cxcl10, in the tumor microenvironment correlates with the influx of activated T cells into the tumor supporting the antitumor immune response." (PMID 29410666, 2018). "One human study showed that a higher frequency of metastatic melanoma samples expressed the CXCL10 gene relative to primary melanoma samples." (PMID 30320116, 2018). "Immunohistochemical study of primary human melanomas showed that upregulation of CXCL10 protein via type 1 interferons and the presence of CXCR3 infiltrating T cells was associated with spontaneous tumor regression." (PMID 30320116, 2018). "This study demonstrates for the first time that PDGFR-alpha strongly inhibits endothelial and melanoma cells proliferation in a CXCL10/IP-10 dependent way, via miR-503 down-regulation." (PMID 27764787, 2016).
melanoma (continued). "For instance, CCL5 and CXCL9 and CXCL10 contributed to the recruitment of CD8 T cells in a mouse model of spontaneous melanoma." (PMID 27096098, 2016). "The α family includes gamma-interferon inducible protein (IP-10/CXCL10), platelet factor 4, IL-1, and melanoma growth stimulatory activity (MGSA/gro/KC)." (PMID 27418745, 2016). "The CXCR3 ligands, CXCL9 and CXCL10, within the LNs of host mice have facilitated metastasis of murine melanoma cells through CXCR3." (PMID 25798946, 2015). "In contrast, several mRNAs encoding known anti-tumor immune mediators or reflective of anti-tumor type I immunity, including IFN-γ, T-bet, CXCL10, and IL-12, were markedly increased in Ptgs2−/− melanomas." (PMID 26343581, 2015). "In a recent study, while analyzing various inflammatory factors, it was reported that levels of serum IL-1β, IFN-gamma and CXCL10 were significantly increased in advanced melanoma patients." (PMID 32309563, 2015). "In particular, increased CXCL10 expression in melanoma tumors results in increased infiltration of adoptively transferred CXCR3-positive expanded NK cells, reflecting the role of CXCL10-induced chemoattraction." (PMID 26441986, 2015). "Another study reported increased plasma CXCL10 in melanoma patients treated with relatively low doses of IFNα associated with a trend towards increased frequency of CD16+ monocytes in vivo." (PMID 22363505, 2012). "The anti-angiogenic factor CXCL10 was additionally increased after rituximab treatment which together with a decreased VEGF level likely contributes to the shrinkage of the melanoma lesions." (PMID 22289880, 2012). "Of interest, a recent study by Mohty and colleagues has shown the increase of CXCL-10 plasma levels in melanoma patients treated with relatively low doses of IFNα, which also parallels a trend towards an increase of CD16+ monocytes." (PMID 21586124, 2011). "On the one hand, the chemokine CXCL9 has been described as a key mediator in homing and metastasis, as confirmed by the fact that expression of CXCL9 and CXCL10 in the lymph nodes facilitates melanoma cell metastasis in a murine model." (PMID 21179030, 2011). "We observed that tumour endothelial cells (ECs) secrete high levels of CXCL9 in all, and CXCL10 in most melanoma metastases." (PMID 21179030, 2011). "The upregulation of CXCL10 in B16 melanoma vessels, as well as significantly increased infiltration of CD3( + ) T‐lymphocytes in B16 tumors, was observed by inhibiting VEGF signaling in mice with B16 melanoma, indicating the closer links between the cytokine and lymphocytes." (PMID 41208700, 2025). "Similarly, nanoparticle-based CXCL10 stimulators are being developed to enhance ICB efficacy in melanoma, further highlighting their clinical applications." (PMID 41516196, 2025). "This dual strategy addresses a critical barrier in treating cold tumors like OS and could potentially be extrapolated to other malignancies where high serum CXCL10 correlates with poor prognosis, such as melanoma and hepatocellular carcinoma." (PMID 41516196, 2025). "Collectively, these results describe that DNMTi-induced ICAM-1 upregulation correlates with a modulation of melanoma secretome in inducing the secretion of the T-cell chemokines CXCL9 and CXCL10 and with the survival positive predictor 12-chemokine melanoma signature." (PMID 39867570, 2025). "Immunokine profiling studies in the CSF of patients with advanced melanoma suggested that increased levels of CXCL10, CCL17, and CCL4 may be correlated with a more aggressive development of BMs." (PMID 39780275, 2025). "Although increased STAT3 and NF-κB activity in IκBζ-expressing melanoma could explain the elevated expression of IL-6 and IL-1 cytokines, STAT3 and NF-κB inhibition was unable to recover IκBζ-mediated suppression of Cxcl9, Cxcl10, and Ccl5 in melanoma cells." (PMID 40562773, 2025). "However, in melanoma cells that strongly express inducible nitric oxide synthase, CXCL10 expression is reduced." (PMID 40211394, 2025).
melanoma (continued). "Techniques such as CRISPR/Cas9-mediated knockout of CXCL10 has demonstrated potential in preclinical models to ‎reduce tumor-promoting inflammation, while nanoparticle-based CXCL10 inhibitors enhance ‎immune checkpoint blockade efficacy in melanoma." (PMID 40760734, 2025). "Notably, human A375 melanoma cells produced a similar base level of CXCL10 and CXCL9 (about 200 pg/ml) but in response to IFN-γ, it showed about a 6-fold increase in CXCL10 production, with no increase in CXCL9 production." (PMID 39474427, 2024). "CXCL9 and CXCL10 genes also play important roles in tumors, such as melanoma and colorectal cancer." (PMID 38448514, 2024). "In addition, single-cell RNA sequencing analysis of tumor-infiltrating immune cells in melanoma patients has shown that macrophages are the predominant source of CXCL10 in the melanoma tumor microenvironment." (PMID 39268223, 2024). "However, the role of host-derived endogenous CXCL10 in melanoma angiogenesis and vertical growth remains elusive." (PMID 39268223, 2024). "Hydrogel‐generated gradients of murine CXCL10, linked to intratumorally injected hydrogel solutions via azidoester linkers, resulted in significant recruitment of CD8+ T‐cells and the attenuation of tumor growth in a “cold” syngeneic melanoma model." (PMID 39553428, 2024). "Cxcl10 mRNA expression levels were significantly higher in melanoma tumors than in normal tissues." (PMID 39268223, 2024). "While much data has accumulated on the role of CXCL10 in melanoma metastasis, its role in primary melanoma tumor growth, particularly its host-derived aspects, and the underlying mechanisms remain unclear." (PMID 39268223, 2024). "In the present study, we found that host-derived endogenous CXCL10 production was dramatically augmented during subcutaneous B16F10 melanoma tumor growth and that host ablation of CXCL10 in Cxcl10-/- mice showed a decrease in both angiogenesis and tumor growth of B16F10 melanoma in vivo." (PMID 39268223, 2024). "Moreover, melanoma patients who express low levels of CXCL9 or CXCL10 (either blood or tumor site) are poor responders to ICT, and those with high levels of CXCL9 or CXCL10 respond more favorably." (PMID 39474427, 2024). "In addition, CXCL10 directly enhanced B16F10 melanoma tumor growth in an in vitro three-dimensional cell culture system." (PMID 39268223, 2024). "Notably, our group has previously demonstrated that melanoma cells can stimulate CXCL10 production from macrophages in a cell-to-cell contact manner and that the augmented production of CXCL10 is required for cancer outgrowth within bone." (PMID 39268223, 2024). "For example, CXCL10 is produced by immune cells and melanoma cells in human melanoma metastases." (PMID 37048082, 2023). "CX3CL1 and CXCL13 were shown to play an important role in the brain extravasation of breast cancer, while the following cytokines/chemokines were involved in the extravasation of melanoma cells (9IL-23, CXCL10, CXCR3, CXCL10 receptor, CCR4, CCL17, and CCR4) and lung cancer cells (TNF-α and CX3CR1)." (PMID 37190188, 2023). "CXCL10 plays an important role in the recruitment of antitumor T-cells in melanoma." (PMID 37569757, 2023). "We and others could also detect a combined functional defect in circulating pDCs of melanoma patients in term of IFN-α and CXCL10 production, associated to poor survival." (PMID 38239354, 2023). "Additionally, a rise in other cytokines, including IFN-α, IFN-γ, IL-10, CCL3, and CXCL10, was seen in both melanoma-treated groups receiving LIVP-RFP or LIVP-FlaB-RFP." (PMID 37112810, 2023). "Similarly, we found an increase in CXCL9 and CXCL10 in the first months of treatment with PD-1 inhibitors in responders with melanoma." (PMID 37569757, 2023). "Furthermore, several recent studies have demonstrated that high CXCL10 level is an indicator of positive response to immune checkpoint blockade (ICB) in melanoma, neuroblastoma, breast and urothelial cancers." (PMID 35207629, 2022).